MTOR (mechanistic target of rapamycin kinase)
Diseases named in the same sentence as MTOR in open-access papers (continued):
Sharing a sentence is not in itself a finding about the gene and the disease.
ovarian carcinoma (continued). "Mechanistically, they promote dephosphorylation of the overactivated phosphatidylinositol 3-kinase/protein kinase B/mammalian target of rapamycin (PI3K/AKT/mTOR) signaling pathway, reverse cisplatin resistance in ovarian cancer, and exert antitumor effects." (PMID 36297672, 2022). "Compared to monotherapy, combined administration of PARPi and EGFR inhibitors has shown better antitumor effects in ovarian cancer A2780 xenografts, mainly through the activation of the ERK (MAPK) and JNK and inhibition of the AKT/mTOR/(p70S6K) pathways." (PMID 35681617, 2022). "Studies have found that HIF-1α silencing can attenuate the viability of hypoxic ovarian cancer cells and increase apoptosis and autophagy through the PI3K/AKT/mTOR signaling pathway." (PMID 36523985, 2022). "In ovarian cancer cell lines, siRNA‐mediated NANOG knockdown diminished migration and invasion properties by regulating the EMT process via the AMPK/mTOR signalling pathway." (PMID 36114703, 2022). "Our data showed that siRNA‐mediated NANOG knockdown drastically inhibited cell migration and invasion as well as the EMT process by activating the AMPK/mTOR signalling pathway in SKOV‐3 and A2780 ovarian cancer cells." (PMID 36114703, 2022). "The combination of a PI3K/mTOR inhibitor (PF502) and MEK inhibitor (PD901) have previously been shown to have a synergistic antiproliferative effect against ovarian cancer cell lines cultured as monolayers." (PMID 35053555, 2022). "Functionally, knockdown of NANOG in ovarian cancer cell lines hindered cell migration and invasion, as well as the EMT process via the AMPK/mTOR signalling pathway." (PMID 36114703, 2022). "In ovarian cancer cells, researchers found that AMPK/mTOR signaling participates in the regulation of ovarian cancer cell migration and invasion by inducing apoptosis." (PMID 34692659, 2021). "AMF represses ovarian cancer and the expression of Skp2 through ROS/AMPK/mTOR signaling pathway in xenograft mouse model." (PMID 35002708, 2021). "In a previous study, we found that IGF1 activates mTOR and limits the antitumor activity of BYL719 in breast and ovarian cancers." (PMID 34067117, 2021). "Knockdown of miR-582-3p promotes the proliferation and migration ability of ovarian cancer and activates the downstream AKT/mTOR signaling pathway, and this promotion is partially abrogated by the knockdown of upstream lncRNA TUG1." (PMID 34793263, 2021). "Among the numerous aberrant oncogenic signaling pathways in ovarian cancer, the PI3K/AKT/mTOR pathway is one of the most frequently altered." (PMID 34793263, 2021). "In this study, OV2008 cell line showed constitutive STAT5 activation and this is because OV2008 cells are an ovarian cancer cells shown to have constitutive active pathways like PTEN, mTOR and Akt." (PMID 34358244, 2021). "Collectively, the present study demonstrates that ATX, and thereby LPA, induces DDR2 expression through the activation of the PI3K/Akt/mTOR/HIF-1α/Twist1 signaling axes, aggravating ovarian cancer cell invasion." (PMID 34065317, 2021). "Knockdown the HIF-1α expression via siRNA in A2780 and SKOV3 cells significantly downregulated the phosphorylation of AKT/mTOR.Besides, AKT pathway regulates the expression of HIF-1α and Herpesvirus entry mediator(HVEM) is overexpressed in ovarian cancer." (PMID 35004308, 2021). "In ovarian cancer, elevated levels of LH promote angiogenesis specifically through the PI3K/Akt-mTOR pathway." (PMID 34867818, 2021). "Several studies investigating PI3K signaling in ovarian cancer have demonstrated enhanced signaling of different nodes of the pathway and how dysregulation of the PI3K/AKT/mTOR pathway contributes to cell proliferation, migration, and chemotherapy resistance." (PMID 35582310, 2021).
ovarian carcinoma (continued). "The schematic signaling pathway of LPA-induced DDR2 expression depicts the upregulation of DDR2 by LPA through coordinate activation of the PI3K/Akt/mTOR/HIF-1α signaling pathways and Twist1 expression to augment ovarian cancer cell invasion." (PMID 34065317, 2021). "Atractylenolide I can also promote ovarian cancer cell cycle arrest and apoptosis by inhibiting the PI3K/Akt/mTOR pathway." (PMID 34335248, 2021). "It had been reported that ivermectin inhibited breast and ovarian cancer cells proliferation by promoting PAK1 ubiquitination degradation and cytostatic autophagy by suppressing Akt/mTOR signaling pathway." (PMID 34876051, 2021). "MCP-1 specifically binds to CCR2 and activates PI3K/AKT/mTOR signaling pathway and its downstream factor hypoxia inducible factor-1α (HIF-1α) and vascular endothelial growth factor -A (VEGF-A), facilitating ovarian cancer cell metastasis to omentum." (PMID 34485124, 2021). "The inhibition of mTOR activity by rapamycin and the reduction of ribosomal protein S6 expression using small interfering RNA (siRNA) inhibited GDH and GLS activity in ovarian cancer cells." (PMID 33542926, 2021). "In ovarian cancer, REST regulates the growth and survival of tumor cells via the regulation of mTOR signaling." (PMID 33834072, 2021). "In breast and ovarian cancer patients, the inhibition of the PI3K/AKT/MTOR pathway with PIK3R1 inhibitors (temsirolimus, ridaforolimus, everolimus) have been shown to satisfactory clinical outcomes of patients with endometrial cancer in Phase II trials." (PMID 34367229, 2021). "We found that PI3K/AKT pathway node proteins (PI3K, AKT, and mTOR), and MAPK pathway node proteins (MEK and ERK) were significantly upregulated in ovarian cancer cells overexpressing YWHAE." (PMID 34107979, 2021). "For example, mTOR (LY-294002 and sirolimus) and PI3K inhibitors (wortmannin) were predicted for the treatment of ovarian cancer." (PMID 33748162, 2021). "Adipocytes secrete monocyte chemotactic protein-1 (MCP-1) to bind C-C motif chemokine receptor 2 (CCR-2) on ovarian cancer cells to activate the PI3K/AKT/mTOR pathway, thereby increasing the expression of HIF-1α, which contributes to ovarian cancer metastasis." (PMID 35004308, 2021). "Several inhibitors of PI3K/Akt/mTOR pathway have been clinically applied to some malignancies including ovarian cancer, and c-Met receptor has been found to promote PI3K/Akt/mTOR pathway and to play an important role in drug resistance." (PMID 32742495, 2020). "The specific autophagic effect mediated by TFS occurred independently from Akt/mTOR/p70S6K pathway signaling and the TFS-induced autophagy in ovarian cancer cells was found to be accompanied by ERK activation and ROS generation." (PMID 33187244, 2020). "We found that metformin reduced ovarian cancer death in two clinical datasets and predicted that the effect of metformin in ovarian cancer was mediated by the AKT/mTOR pathway using a bioinformatics model." (PMID 32825834, 2020). "Inhibition of the AKT/mTOR pathway by the dual inhibitors, GSK458, AZD2014 and BEZ235 reduced cell invasion and migration in thyroid, pancreatic, and ovarian cancer in preclinical models." (PMID 33659215, 2020). "Eclalbasaponin II has the ability to arrest cell cycle in the G1 phase, induced apoptosis and cell death through autophagy by regulating the JNK, p38, and mTOR signaling pathways in SKOV3 and A2780 human ovarian cancer cells." (PMID 33552000, 2020). "Nevertheless, the utilization of dual-targeted inhibitors for PI3K/AKT/mTOR and RAS/ERK signaling pathways is a potentially effective therapeutic approach against ovarian cancer." (PMID 32429466, 2020). "In ovarian cancer, increased PI3K activation, as measured by mammalian target of rapamycin (mTOR) phosphorylation levels, is seen in all stages of clear-cell carcinoma, and is considered to be an early event." (PMID 32961868, 2020).
ovarian carcinoma (continued). "This pathway activation is associated with higher invasive and migratory capacities in human ovarian cancer; thus, the PI3K/Akt/mTOR pathway is a potential predictor of invasiveness in ovarian-tumor cells." (PMID 32604863, 2020). "Ongoing clinical trials in ovarian cancer are evaluating inhibitors of multiple molecular pathways such as PI3K/AKT, the mTOR pathway, angiogenesis, the MAPK pathway, and the HER/EGFR pathway." (PMID 33256002, 2020). "Qiao et al10 reported that the NF1 overexpression induced autophagy and inhibited mTOR/P70S6K signalling in ovarian carcinoma cells and in turn inhibited ovarian carcinoma cell proliferation and invasion." (PMID 32862562, 2020). "The phosphorylation measures of AKT (upstream of mTOR) and P70-S6 kinase (downstream of mTOR) were each expanded upon LNK overexpression, which suggests that the mTOR pathway is upregulated via LNK in ovarian cancer cells." (PMID 32322171, 2020). "A recent report suggested that GRP78 inhibition in ovarian cancer cells blocked ER stress and autophagy activation induced by diindolylmethane and inhibited AMPK via mTOR activation." (PMID 32879309, 2020). "In the present study, knockdown of HVEM markedly blocked the activation of AKT and mTOR, while overexpression of HVEM significantly promoted the signaling of AKT and mTOR in OVCAR3 cells and primary ovarian cancer cells further." (PMID 32312328, 2020). "By inhibiting mTOR, DHA induced autophagy and apoptosis in cisplatin-resistant ovarian cancer cells." (PMID 31569540, 2019). "Overexpression of PBK attenuated ovarian cancer cell sensitivity to cisplatin treatment and promoted autophagy flow through the ERK/mTOR axis." (PMID 30778048, 2019). "This study investigated the antitumour effects of two dual mTOR/PI3K inhibitors, gedatolisib (WYE-129587/PKI-587/PF-05212384) and PF-04691502 against a panel of six human patient derived ovarian cancer xenograft models." (PMID 31822716, 2019). "On the other hand, a gradual reduction of AMPK activation due to the subsequent high ATP production led to the activation of mTOR and TAK1/NF-κB signaling, which in turn, enhanced ovarian cancer metastasis and aggressiveness." (PMID 31372520, 2019). "A recent study reported that EMT and CSC marker expression were significantly increased in chemoresistant ovarian cancer cells, accompanied by the activation of PI3K/AKT/mTOR signaling." (PMID 31569540, 2019). "In ovarian cancer (OC), the increased expression of HSP60 enhances tumor progression by stabilizing mitochondrial homeostasis and activating mTOR signaling pathway." (PMID 31878360, 2019). "To elucidate the potential mechanism of how STAT3 activation inhibited autophagy in ovarian cancer cells, we detected major members in MAPK and PI3K/AKT/mTOR signal networks by western blot." (PMID 31597912, 2019). "Overexpression of CASC2 inhibited epithelial ovarian cancer development by inhibiting EIF4A3 expression and suppressing the PI3K/AKT/mammalian target of rapamycin (mTOR) pathway." (PMID 31134151, 2019). "We confirmed these results, noting significant downregulation of p-AKT, p-ERK, p-mTOR, p-ULK1, p-P70S6K in A2780 ovarian cancer cells following both amino acid deprivation as well as complete serum starvation (HBSS supplemented with 3% glucose) at 2–4 h." (PMID 31052266, 2019). "In summary, a diet that was high in plant protein reduced the growth of human HM-1 and ID-8 ovarian cancer cells in mice in comparison to a diet that was high in animal protein, ―possibly through the relative inhibition of the IGF/Akt/mTOR pathway." (PMID 29844867, 2018). "It had been reported that GDF15 stimulated ovarian cancer cell growth and invasion through AKT/mTOR and MAPK signaling." (PMID 28199981, 2017).
ovarian carcinoma (continued). "Moreover, PI3Kα and Twist positive CTCs could be an attractive therapeutic target, since PI3K/Akt/mTOR pathway inhibitors are currently being investigated for ovarian cancer among several preclinical studies and also a few ongoing clinical trials (NCT01623349, NCT02476955)." (PMID 28415744, 2017). "Addressing this issue therapeutically, we show that a pharmacological approach combining a DYRK1B antagonist with an mTOR/AKT inhibitor results in strong GLI1 targeting and in pronounced cytotoxicity in human pancreatic and ovarian cancer cells." (PMID 27903983, 2017). "In-depth analysis of BCL-2 family proteins and other apoptotic regulators in response to PI3K/mTOR pathway blockade identifies BIM, caspase-3, BCL-XL, XIAP, and MCL-1 as critical players in ovarian cancer cell survival." (PMID 28848242, 2017). "In summary, AE2 was overexpressed in ovarian cancer samples, and up-regulated AE2 expression can activate the mTOR/p70S6K1 pathway, promoting ovarian cancer cell growth." (PMID 28743911, 2017). "In ovarian cancer, aberrant activation of the PI3K/Akt/mTOR pathway has also been reported and EMT is supposed to promote chemo-resistance." (PMID 28415744, 2017). "The observation that niclosamide can target the Wnt, mTOR and STAT3 pathways and reverse platinum resistance, provides compelling evidence to consider clinical studies with niclosamide in patients with ovarian cancer." (PMID 27888804, 2016). "In in-vitro studies of ovarian cancer cells, cisplatin addition leads to AKT phosphorylation and AKT/mTOR pathway induction." (PMID 27090655, 2016). "We first evaluated the effect of BEZ235 and Bay 65–1942 treatment individually or in combination on the PI3K/mTOR signaling and IKKβ target gene expression in FUOV1, NIH:OVCAR3 and IGROV1 ovarian cancer cells." (PMID 26657155, 2016). "Inhibition of AKT/mTOR/(p70S6K) signaling pathway and activation of MAPK (ERK), JNK and AMPK signaling pathways increased autophagy-induced cell apoptosis in ovarian cancer." (PMID 27825125, 2016). "Collectively, we have established the role of mTOR signalling in age-related OSE pathologies and initiation of ovarian cancer." (PMID 27036037, 2016). "Everolimus exhibited a significant decrease in inhibition of mTOR/S6 activity for the cells incubated under the hyperglycemic condition, indicating that phosphorylation of S6 may be involved in sensitivity to everolimus under different glucose conditions in ovarian cancer cells." (PMID 26959121, 2016). "Similar effects were observed in our orthotopic mouse model of ovarian cancer, which demonstrated that simvastatin blocked tumor growth via inhibition of the MAPK and mTOR/S6 pathways and activation of the mitochondrial apoptosis pathway." (PMID 26503475, 2016). "Clinical trials are evaluating mTOR inhibitors, Wnt inhibitors, and STAT3 inhibitors in ovarian cancer and other solid tumors." (PMID 27888804, 2016). "The constitutive activation in ovarian cancer is a result of amplification of pathway components like PI3K subunits (p110), AKT isoforms (AKT1, AKT2, or AKT3), or members of the mTOR complexes (RICTOR, RAPTOR)." (PMID 27090655, 2016). "In this current study we demonstrate that niclosamide not only targets the Wnt pathway, but it also targets the mTOR and the STAT3 pathways and specifically targets CD133+ CSCs and chemoresistant cells isolated from a PDX ovarian cancer model." (PMID 27888804, 2016). "Ovarian cancer cells, including SKOV3 cancer cell line, exhibit constitutive activation of Akt/mTOR survival pathway, thus protecting the cancer cells from apoptosis." (PMID 28066412, 2016). "The PI3K/mTOR dual inhibitor NVP-BEZ235 reduced Mcl-1 expression and sensitized ovarian carcinoma cells to ABT-737 through a Bim-dependent mechanism." (PMID 26405162, 2015).
ovarian carcinoma (continued). "The increased expression of miR-214 is involved in cisplatin resistance in ovarian cancer by down-regulation of PTEN protein and activation of the PI3K/AKT/mTOR pathway, thereby enhancing cell survival." (PMID 26779370, 2015). "The dual PI3K/mTOR inhibitor NVP-BEZ235 that decreases Mcl-1 expression, synergized with ABT-737 in inducing apoptosis of ovarian carcinoma cells, provided that Bim expression was induced." (PMID 26405162, 2015). "Therefore the PI3K-AKT pathway may also participate in EMT which was mediated by down-regulation of RASAL2, raising the possibility that the PI3K-AKT pathway inhibitors or mTOR pathway inhibitors, such as rapamycin, may also be effective in the treatment of Ras pathway-activated ovarian cancer." (PMID 25216515, 2014). "Earlier studies showed that inhibitors of mTOR increase Mirk kinase expression, and the combination of a Mirk kinase inhibitor and the mTOR inhibitor RAD001 killed more SKOV3 and TOV21G ovarian cancer cells than either agent alone." (PMID 25061503, 2014). "Ours findings that early imaging with FLT rather than FDG predicts later tumor volume is supported by other preclinical studies demonstrating that mTOR-inhibition is better predicted by FLT than FDG in lymphoma cell lines and ovarian cancer cell lines." (PMID 24626055, 2014). "The mammalian target of rapamycin (mTOR) is a major component of the PI3K/Akt signaling pathway that is frequently dysregulated in various types of cancer, including ovarian cancer." (PMID 25153728, 2014). "Recent studies also suggest that P70S6 kinase, downstream of mTOR, drives the expression of HIF-1α and VEGF in human ovarian cancer, mediating tumor growth and angiogenesis." (PMID 24722367, 2014). "Taken together, our results indicate that the FGF2-dependent PI3K/Akt/mTOR and MAPK/ERK activation is involved in FGF2-induced E-cadherin down-regulation and cell invasion in ovarian cancer cells." (PMID 23554977, 2013). "In the development and progression of ovarian cancer, it is clear that the PI3K/AKT/mTOR pathway plays an instrumental role." (PMID 23591839, 2013). "This study demonstrates a novel mechanism in which FGF2 down-regulates E-cadherin expression through the activation of PI3K/Akt/mTOR and MAPK/ERK signaling, and the up-regulation of Slug and ZEB1 in human ovarian cancer cells." (PMID 23554977, 2013). "In contrast, activated AKT was a predictive marker of drug sensitivity in ovarian cancer cells, which were treated with RAD001 (everolimus) to inhibit the mTOR pathway." (PMID 24036443, 2013). "The findings of this study indicate that not only can changes in the PI3K/AKT/mTOR pathway provide prognostic factors about survival, but also that genetic activation of the PI3K/AKT/mTOR pathway is an important characteristic of ovarian cancer." (PMID 23591839, 2013). "Taken together, our findings indicate that FGF2 differentially regulates Slug and ZEB1 expression via the PI3K/Akt/mTOR and MAPK/ERK signaling pathways in human ovarian cancer cells." (PMID 23554977, 2013). "In the chemoresistant ovarian cancer cells, SKOV3/DDP and SKOV3/MCA, elevated activation of the AKT/mTOR/survivin signaling was observed." (PMID 24137412, 2013). "Further studies are warranted to understand better the mTOR/P70S6K pathway in the context of MT dynamics and ovarian cancer." (PMID 23819061, 2013). "Re-expression of ARHI in multiple human ovarian cancer cell lines induces autophagy by blocking PI3K signaling, inhibiting mammalian target of rapamycin (mTOR), and upregulating ATG4." (PMID 21244707, 2011). "We have studied the activation of PI3-K, mTOR and MEK signaling in ovarian cancer cells treated with HSP90 inhibitor." (PMID 21962244, 2011).